MBD3 (methyl-CpG binding domain protein 3)
Diseases named in the same sentence as MBD3 in open-access papers (continued):
Sharing a sentence is not in itself a finding about the gene and the disease.
glioblastoma (2 papers, 2024 to 2025). The most malignant astrocytic tumor (WHO grade IV). "Experimental evidence has demonstrated the anti-proliferative role of MBD3, acting as a protective mechanism against glioblastoma development." (PMID 38539439, 2024). "Methyl-CpG Binding Domain Protein 3 (MBD3) depletion leads to the dysregulation of Breast Cancer Gene 1 (BRCA1) alternative splicing via a long non-coding RNA in glioblastoma cells." (PMID 38539439, 2024). "This Wnt–Mbd3 branch provides new insights into the neurogenesis regulatory circuit governed by canonical Wnt signaling, paving the way for potential improvements in therapeutic strategies for treating neurodegenerative diseases and glioblastoma through regenerative approaches." (PMID 40750707, 2025).
glioma (2 papers, 2016 to 2022). A benign or malignant brain and spinal cord tumor that arises from glial cells (astrocytes, oligodendrocytes, ependymal cells). "5hmC has been discovered as a major DNA modification in association with MBD3 and some efforts aimed to exploit the clinical implication of 5hmC in glioma have been attempted." (PMID 27835581, 2016). "We anticipate that glioma tissues with relatively more MBD3 would respond better to therapeutic vaccination and immune-checkpoint-blockade agents (e.g., PD-1/PD-1L inhibitors and CTLA-4 blockade)." (PMID 27835581, 2016). "Encouragingly, we noted that a correlated enrichment of MBD3 and 5hmC (the preferable binding site of MBD3 in brain tissues) within glioma cells indicated a better PFS and OS in patients, which confers a promising basis for future large-scale clinical studies." (PMID 27835581, 2016). "For example, our results suggest that MBD3 is required for the expression of MHC (major histocompatibility complex) class II molecules which were proposed as key factors mediating anti-glioma immunity." (PMID 27835581, 2016). "This set of experiments indicates a non-redundancy or insufficient expression of endogenous MBD3 in human glioma, which gives rise to the binding space for exogenous MBD3 molecules." (PMID 27835581, 2016). "In this study, we examine the genome-wide transcriptome regulated by MBD3 and its relevant implications to the survival of glioma patients." (PMID 27835581, 2016). "Following the experiments at the molecular and cellular levels, we explored the possibility of using MBD3 as a potential prognostic biomarker due to its control on glioma migration and proliferation." (PMID 27835581, 2016). "The regulatory effects of MBD3 on glioma transcriptome were first profiled by high-throughput microarray." (PMID 27835581, 2016). "In glioma, the epigenetic modulation by MBD3 is bidirectional: it is connected to both active and silenced genes." (PMID 27835581, 2016). "In order to assess the functional insufficiency of MBD3 in human glioma (i.e., inadequate chromatin deposition), we first utilized single-molecule fluorescence correlation spectroscopy (FCS) to evaluate the biophysical occupancy of the transfected MBD3-GFP in SF767 GBM cells." (PMID 27835581, 2016). "A considerable overlap in the impacted protein functions between these two sets of DEGs is noted, which implicates that during the progression from low-grade to high-grade gliomas, MBD3 is involved in a substantial portion of gliomagenetic pathways and functions." (PMID 27835581, 2016). "Our bioinformatics and experiment data supports that maintenance of the MBD3 abundance might herald a better prognosis for glioma patients." (PMID 27835581, 2016). "This study further suggests a MBD3-mediated anti-glioma network." (PMID 27835581, 2016). "Interestingly, the expression of MBD3 shares the reducing pattern with the 5hmC quantity in high-grade glioma." (PMID 27835581, 2016). "Interestingly, the enrichment of MBD3 or the 5mC-binding protein MBD2 indicates entirely opposite outcomes in the glioma survival even though they share a >70% similarity in protein sequences." (PMID 27835581, 2016). "We show that MBD3 can complement 5hmC in prediction of glioma prognosis." (PMID 27835581, 2016). "Furthermore, MBD3 fine-controls a spectrum of proteins critical for cellular metabolism and proliferation, thereby contributing to an exquisite anti-glioma network." (PMID 27835581, 2016). "In analysis of the up-regulated DEGs, the major differences between low-grade glioma and GBM are “nucleic acid binding proteins” and “transcription factors”, while depleting MBD3 further disturbs the expression of some “receptor proteins” (e.g., G-protein coupled receptors) in GBM cells." (PMID 27835581, 2016).
glioma (continued). "Following this line of findings, a negative correlation between the WHO grade of glioma and the MBD3 abundance was further revealed." (PMID 27835581, 2016). "Besides protein, the MBD3 mRNA extracted from clinical samples was quantified by qRT-PCR; however, no direct correlation was noted between the MBD3 transcripts and glioma grade, implicating a decreased efficiency of mRNA translation or an increased rate of protein degradation in high-grade gliomas." (PMID 27835581, 2016).
leukemia (2 papers, 2016 to 2023). A malignant (clonal) hematologic disorder, involving hematopoietic stem cells and characterized by the presence of primitive or atypical myeloid or lymphoid cells in the bone marrow and the blood. "These efforts and additional validation experiments revealed PSIP1, CREBBP, and kinase FLT3 representing known vulnerabilities in KMT2A-r, as well as ARID4B, MBD3, and BMPR2 as potential candidates to be considered as novel therapeutic targets in this aggressive type of leukemia." (PMID 37686014, 2023).
lupus (2 papers, 2017 to 2023). "Other investigators described significantly higher mRNA levels of other enzymes (MBD1, MBD3, and MBD4), involved in the DNA methylation process, in patients with lupus." (PMID 28349196, 2017).
systemic sclerosis (2 papers, 2018 to 2025). A chronic disorder, possibly autoimmune, marked by excessive production of collagen which results in hardening and thickening of body tissues. "In SSc (systemic sclerosis), the expression of other MBD family molecules, such as the mRNA of MBD3 and MBD4, is reduced compared to controls, and a positive correlation exists between the relative levels of MBD4 and DNA methylation in the SSc group." (PMID 40533455, 2025).
cerebral infarction (1 paper, 2022). An ischemic condition of the brain, producing a persistent focal neurological deficit in the area of distribution of the cerebral arteries. "Confirming these changes, the MBD2/MBD3 ratio and neuronal cell death were significantly increased in the hippocampal CA1 area at 24 h after cerebral infarction, whereas there was no change in apoptosis or the MBD2/MBD3 ratio in the DG." (PMID 36142283, 2022).
colorectal tumor (1 paper, 2019). "Recent study showed that MBD3 is a target of miR-8073, which is reported to be a colorectal tumor suppressor." (PMID 31998373, 2019).
dermatomyositis (1 paper, 2016). Dermatomyositis (DM) is a type of idiopathic inflammatory myopathy characterized by evocative skin lesions and symmetrical proximal muscle weakness. "The NuRD multiprotein complex includes the dermatomyositis-specific Mi2 autoantigen (Mi2-β), RB-associated proteins 46 and 48 (RbAp46 and RbAp48), MBD2 and MBD3, and metastasis-associated proteins 2 and 3 (MTA2 and MTA3)." (PMID 26810492, 2016).
developmental delay (1 paper, 2018). "Simultaneous injection of Y3 MO and MBD3-specific IgGs resulted in developmental delay before the MBT, as seen with inhibition of MBD alone, but the severity of the phenotype was increased and the onset of embryonic death accelerated." (PMID 29490265, 2018).
Diamond-Blackfan anemia (1 paper, 2023). A congenital aregenerative and often macrocytic anemia with erythroblastopenia. "DAZAP1 and MBD3 do not currently show any evidence for their involvement in CHD; however, a missense mutation in RPS15 has been described as a possible causal candidate in a patient with complex CHD as part of Diamond Blackfan anemia." (PMID 37887000, 2023).
epilepsy (1 paper, 2016). A brain disorder characterized by episodes of abnormally increased neuronal discharge resulting in transient episodes of sensory or motor neurological dysfunction, or psychic dysfunction. "Interestingly, several genes that were targeted by MBD3/NuRD in the present study have been linked to epilepsy." (PMID 27650712, 2016). "Further studies on the cooperation between the MBD3/NuRD complex and other DNA binding proteins during epileptogenesis are warranted to better understand the role of MBD3 in the development of epilepsy." (PMID 27650712, 2016). "Our data demonstrate for the first time alterations in the MBD3 expression and DNA occupancy in the experimental model of epilepsy." (PMID 27650712, 2016). "The aim of the present study was to examine involvement of MBD3 (methyl-CpG-binding domain protein 3), a protein involved in reading DNA methylation patterns, in epileptogenesis and epilepsy." (PMID 27650712, 2016). "The relevance of changes in MBD3 expression and DNA occupancy for the pathological events undergoing in the brain during epileptogenesis and epilepsy is not clear." (PMID 27650712, 2016). "However, no data are available on the involvement of MBD3/NuRD in epilepsy." (PMID 27650712, 2016).
hepatitis B (1 paper, 2022). "The MBD3 expression was not significantly correlated with gender, age, drinking history, hepatitis B, liver cirrhosis, lymph node metastasis or tumour size and number." (PMID 35501390, 2022).
influenza (1 paper, 2014). An acute viral infection of the respiratory tract, occurring in isolated cases, in epidemics, or in pandemics; it is caused by serologically different strains of viruses (influenzaviruses) designated A, B, and C, has a 3-day incubation period, and usually lasts for 3 to 10 days. "We have adopted intramuscular injection to deliver eukaryotic expression vector in this study, and all the results have shown that the recombinant mBD1/mBD3 expressed in the muscle manifest anti-influenza in the lung indeed." (PMID 24632574, 2014).
ischemia (1 paper, 2016). A hypoperfusion of the BLOOD through an organ or tissue caused by a PATHOLOGIC CONSTRICTION or obstruction of its BLOOD VESSELS, or an absence of BLOOD CIRCULATION. "Considering the neuronal localization of MBD3, we posit this was attributable to massive ischemia-induced neurodegeneration." (PMID 27650712, 2016).
lentivirus infection (1 paper, 2009). Virus diseases caused by the Lentivirus genus. "To circumvent this drawback of transient transfection for in vivo assays, we made stable Mbd3 knockdown ES cell lines by lentivirus infection." (PMID 19888462, 2009).
malignant glioma (1 paper, 2016). A grade III or grade IV glioma arising from the central nervous system. "Taken together, this work enriches our understanding of the mechanistic involvement of MBD3 in malignant glioma." (PMID 27835581, 2016). "Having followed up a pilot cohort, we noted that the survival of malignant glioma patients was proportional to the content of MBD3 and 5-hydroxymethylcytosine (5hmC) in their tumor cells." (PMID 27835581, 2016). "In malignant glioma, MBD3 is also prevalently expressed but the average level negatively correlates with the WHO grade." (PMID 27835581, 2016). "In this article we inspect the roles and functions of the methyl-CpG-binding domain protein 3 (MBD3) in human malignant glioma, to assess its potential as an epigenetic biomarker for prognosis." (PMID 27835581, 2016). "Therefore, this set of data supports the potential of MBD3 as a novel epigenetic marker to complement 5hmC in the clinical management of malignant glioma." (PMID 27835581, 2016).
malignant glioma of the brain (1 paper, 2016). "Increased expression of MBD3 and MBD4 were associated with malignant glioma of the brain, and the grade of malignancy correlated with MBD3/4 expression level." (PMID 27446199, 2016).
myeloma (1 paper, 2022). "In line, MBD3 silencing by siRNA resulted in an increase in the clonogenic potential in myeloma cell lines." (PMID 36059621, 2022). "Further analysis revealed increased SOX2 and decreased levels of the methylation reader MBD3 in this population of residual myeloma cells, together with a clear deregulation of embryonal stem cell pathways." (PMID 36059621, 2022).
neuropathy (1 paper, 2022). A disorder affecting the nervous system that manifests with pain, tingling, numbness, and/or muscle weakness. "Alterations in MBD3 have been related to PD and to Neuropathy, Hereditary Sensory, Type Ie in the GeneCards database." (PMID 36414996, 2022).
stomach adenocarcinoma (1 paper, 2024). "The pan-cancer analysis showed that MBD3 was highly expressed in most types of cancers, including GBM, COAD and STAD (stomach adenocarcinoma, belonging to GC)." (PMID 38178023, 2024).
temporal lobe epilepsy (1 paper, 2016). A localization-related (focal) form of epilepsy characterized by recurrent seizures that arise from foci within the temporal lobe, most commonly from its mesial aspect. "The present study was designed to evaluate whether MBD3 protein is involved in temporal lobe epilepsy pathology in an experimental rat model." (PMID 27650712, 2016).
uterine serous carcinoma (1 paper, 2013). "Recently, whole-exome sequencing revealed high-frequency deletion of a short segment of chromosome 19 containing the MBD3 locus in uterine serous carcinoma and frequent point mutations in CHD4 in serous endometrial tumors, suggesting fundamental functions of NuRD in primary tumors." (PMID 24385926, 2013).
viral infection (1 paper, 2024). "Also, the localization of the MBD2/MBD3 NuRD Complex in the context of viral infection will provide new perspective on comprehending the cellular and molecular pathways influenced by HPV16 E6/E7 oncoproteins." (PMID 38790189, 2024).
Wilson disease (1 paper, 2016). A very rare inherited multisystemic disease presenting non-specific neurological, hepatic, psychiatric or osseo-muscular manifestations due to excessive copper deposition in the body. "For ATP7B, 15 (three silent, 12 Wilson disease-causing) variants in MBD3 are described." (PMID 26747866, 2016).
cancer (25 papers, 2004 to 2024). A tumor composed of atypical neoplastic, often pleomorphic cells that invade other tissues. "Pan-cancer analysis has revealed differential expression of MBD3 in various tumors, significantly associated with tumor occurrence, growth, and progression." (PMID 37370795, 2023). "Mutations within MBD3 were associated with human cancer and neurocognitive disorders, such as autistic spectrum disorders (ASDs)." (PMID 34692086, 2020). "Many studies have attempted to link loss of MBD2 or MBD3 to significantly increased cancer predisposition in human patients, but evidence for this is limited." (PMID 27303433, 2016). "Furthermore, MBD3 suppression modulated the H3K27ac signal at genes associated with pathways that are known to be aberrantly activated in cancer, such as cell cycle and proliferation pathways, DNA damage and repair, immune response and EMT-associated pathways." (PMID 34359703, 2021). "Methyl-CpG binding domain protein 3 (MBD3), a key epigenetic regulator, is abnormally expressed in several cancers, participating in progression and metastasis." (PMID 38178023, 2024). "MBD3 was previously found to play a key role in embryonic stem cell pluripotency and can also participate in the process of cancers." (PMID 38178023, 2024). "Pan-cancer analysis revealed MBD3’s differential expression in various tumors and its significant association with tumor occurrence, growth, and progression." (PMID 37370795, 2023). "Dysregulation of MBD3 expression or function has been observed in different human cancers, suggesting its involvement in tumorigenesis and cancer progression." (PMID 37686014, 2023). "We also found that MBD3 expression was significantly correlated with advanced cancer biology, indicated by early vascular invasion and late clinical-stage TNM." (PMID 35501390, 2022). "This went a step further from the previous findings that MBD3-bound gene loci highly overlapped with 5hmC-rich chromosomal regions, which might mechanistically underlie why MBD3 mutations or aberrances in the 5hmC distribution pattern were associated with human disease, including cancer and ASD." (PMID 34692086, 2020). "Although the reprogramming mechanisms of somatic cells and cancer cells are distinct, our results elucidate the function of MBD3 and c-JUN in reprogramming." (PMID 27894081, 2017). "Mbd3/NuRD was previously shown to play a role in methylation of promoter-proximal regions in cancer cell lines by helping recruit DNA methyltransferase enzymes to specific loci." (PMID 27849519, 2016). "SAGE analysis shows that FBI-1 and MBD3 are expressed ubiquitously in most human tissues, with increased expression in various cancer tissues." (PMID 23658227, 2013). "Studies have found that MBD3 plays different roles in different types of cancer." (PMID 38178023, 2024). "Methyl-CpG-binding domain protein 3 (MBD3) is part of the methyl-CpG-binding domain family, which interact with methylated CpG dinucleotides and are implicated in neurological disorders and several cancers, including liver, pancreatic, and colon." (PMID 38674069, 2024). "We explored the relative expression of MBD3 in cancer tissues and adjacent tissues." (PMID 37370795, 2023). "Here, we provided evidence and expanded on previous results by showing that peptides targeting Atox1 and/or ATP7B MBD3/4 can preferentially elicit cancer cell death when administered in the μM range, owing to an increase in copper concentration within the cell." (PMID 36299299, 2022). "Moreover, knockdown of MBD3 gene promoted cancer cell migration and invasion while overexpression inhibited those effects." (PMID 31245293, 2019). "While anti-cancer targeting of c-Jun may serve as a viable and attractive strategy to induce MBD3 expression, further research is needed in this regard." (PMID 31245293, 2019).